MDM2 (MDM2 proto-oncogene)
Diseases named in the same sentence as MDM2 in open-access papers (continued):
Sharing a sentence is not in itself a finding about the gene and the disease.
glioma (continued). "LncRNA PDIA3P1 could stabilize C/EBPβ protein by disrupting the C/EBPβ- MDM2 complex and avoiding ubiquitination of C/EBPβ protein by MDM2, which reduces the sensitivity of glioma cells to temozolomide treatment." (PMID 39022688, 2024). "The results obtained indicated that the knockdown of BAX or PUMA was sufficient to reduce cell death and inhibit caspase activation induced by the RG7112 treatment, suggesting that BAX and PUMA were both required for the apoptotic death of glioma stem cells induced by the inhibition of MDM2." (PMID 38612758, 2024). "Therefore, MDM2 was more highly expressed in glioma stem cells than in non-stem glioma or normal cells, which prompted us to investigate its role in glioma stem cells." (PMID 38612758, 2024). "Previous studies using glioma stem cell lines demonstrated that glioma stem cells were highly sensitive to novel inhibitors of MDM2, such as AMG232 and BI-907828, which was consistent with the present study conducted by inhibiting MDM2 both genetically and pharmacologically using RG7112." (PMID 38612758, 2024). "GISTIC 2.0 analysis revealed that in gliomas with high-risk scores, the amplification mainly occurred in chromosomal regions 1q32.1, 3q26.33, 4q12, 7p11.2, and 12q14.1, where several key oncogenes (PDGFRA, EGFR, MDM2, SOX2, and CDK4) were located." (PMID 35116021, 2021). "AEG-1 interacts with MDM2 resulting in MDM2 stabilization In 86 human glioma samples, IHC analysis revealed that AEG-1, MDM2 and Ki-67 expression levels progressively increased from grade II to grade IV and a positive correlation between AEG-1 and MDM2 expression was observed (p < 0.01)." (PMID 33671513, 2021).
glioma (continued). "For example, those infiltrating gliomas with FGFR-TACC fusions may present with other oncogenic alterations including CDKN2A loss, CDK4 amplification, MDM2 amplification and/or TERT promoter mutations." (PMID 32493417, 2020). "Moreover, the ctDNAs in the metastatic brain tumors included ALK and MDM2, and glioma-related ctDNAs included 1p/19q and MDM2 followed by frequencies of ERBB2, IDH1, CDKN2A, CDK4, PDGFRA, CCNE1, MET." (PMID 32973641, 2020). "Glioma-related ctDNAs included 1p/19q, MDM2, ERBB2, IDH1, CDKN2A, CDK4, PDGFRA, CCNE1, MET." (PMID 32973641, 2020). "More importantly, the restoration of MDM2 via enforced overexpression markedly rescues miR-585 inhibitory effect on human glioma cell proliferation, thus demonstrating that targeting MDM2 is a critical mechanism by which miR-585 inhibits human glioma cell proliferation." (PMID 33005102, 2020). "We further demonstrate that MDM2 is a direct target of miR-585 in glioma cells, and that the restoration of MDM2 substantially rescues miR-585 effect on glioma cell proliferation, thus establishing that the inhibitory effect of miR-585 on glioma cell proliferation depends on directly targeting MDM2." (PMID 33005102, 2020). "It has also been shown that miR-610 and long non-coding RNA ENST00462717 inhibit glioma cell proliferation by targeting MDM2, which are in agreement with our findings and collectively indicate that MDM2 plays a vital role in maintaining or even promoting glioma cell proliferation." (PMID 33005102, 2020). "However, MDM2 levels in glioma tissues at ZT8 were higher than at ZT12 in normal brain tissues when cry2 expression was highest (t=-5.047, p<0.001)." (PMID 29100427, 2017). "While CMIP acts as a tumor promoter in glioma, MDM2 is also reported to be an oncogene." (PMID 28744466, 2017). "Similarly, MDM2 levels were higher at ZT4 in glioma tissues compared to ZT24 in normal brain tissues when cry2 expression was lowest (t=-4.361, p<0.001)." (PMID 29100427, 2017). "Thus, we demonstrated that miR-181b enhances glioma cell sensitivity to teniposide through targeting E3-ligase MDM2." (PMID 25151861, 2014). "In this context, it would be of practical interest and importance to examine whether AMG232 and BI-907828, novel MDM2 inhibitors demonstrated to be highly potent in glioma stem cells, have such a marked differential effect in stem and non-stem glioma cells as RG7112 does." (PMID 38612758, 2024). "To establish whether the increased expression of BAX and PUMA plays an essential role in the apoptotic death of glioma stem cells induced by the inhibition of MDM2, we knocked down BAX and PUMA and examined their effects on the apoptotic death of glioma stem cells treated with RG7112." (PMID 38612758, 2024).
glioma (continued). "Moreover, MDM2 is also involved in the regulation of apoptosis and chemoresistance of glioma cells." (PMID 33005102, 2020). "Therefore, it can be concluded that MDM2 contributes to the oncogenic role of CMIP in human glioma." (PMID 28744466, 2017). "The MDM2 gene, according to the GEPIA2 database, was substantially elevated in brain and CNS cancer compared to matched normal tissues." (PMID 37049742, 2023). "The MDM2-MDMX complex regulates lipid peroxidation and promotes ferroptosis in glioma cells by altering the activity of PPARα." (PMID 36185243, 2022). "A positive correlation between AEG-1 and MDM2 was observed and their expression levels were correlated with poor overall survival concluding AEG-1 and MDM2 as significant prognostic factors for glioma." (PMID 34203598, 2021). "In another study, IHC analysis on 86 human glioma cases revealed that there is a progressive increase in the levels of both AEG-1 and MDM2." (PMID 34203598, 2021). "We next repeated this process for each grade of glioma and found that these enhancers regulated a number of cancer-related genes, such as ARID1B 39, EGFR, MDM2 40, PRGFRA, and MYC." (PMID 33537074, 2021). "In the de Novo pathway of glioma occurrence, two crucial oncogenes (EGFR and MDM2) and two important tumor suppressors (PTEN and IKN4a/ARF) were found to be closely correlated with WNT5A in glioma." (PMID 32181818, 2020). "Here we demonstrate that glioma organoids and PDOXs accurately maintain distinct genetic backgrounds of parental tumors, including gene amplifications of EGFR, PDGFRA, MET, MDM2/4, and CDK4/6, which are difficult to derive and preserve in vitro." (PMID 33009951, 2020). "Exosomes derived from the peripheral blood samples of human glioma patients are reported to carry GBM-specific gDNA of ERBB2, CDK4, AKT3, MDM2, and RB1 genes." (PMID 33137926, 2020). "Looking into well-known oncogenes and TSGs, we identified gains of EGFR in “de novo glioma pathway” (2 in LGG and 3 in HGG), as well as MDM2 (1 in LGG and 3 in HGG) and PTEN (1 in HGG), and losses of CDKN2A (2 in HGG)." (PMID 23451178, 2013). "For example, lower amounts than expected regarding mRNA levels are noted for MDH1 in GBM and SIRT1 in gliomas; or the protein concentration was increased in glioma tissues, although the mRNA was only slightly modified (typically CCPG1, BCL2, MDM2 and PTBP1)." (PMID 21655185, 2011).
glioma (continued). "Consistent with its protein expression, an RT-PCR analysis showed that the mRNA expression of MDM2 was higher in glioma stem cells than in their non-stem cell counterparts." (PMID 38612758, 2024). "We investigated MDM2 expression levels in glioma stem cells and their non-stem cell counterparts and the effects of the genetic and pharmacological inhibition of MDM2 on the viability of these cells as well as downstream molecular pathways." (PMID 38612758, 2024). "In the present study, we investigated the effects of inhibiting MDM2 on the non-stem cell progeny of glioma stem cells for the first time." (PMID 38612758, 2024). "This study compared MDM2 gene mRNA expression patterns in different types of cancer samples, particularly in LGG cancer samples, with their comparable normal samples, which were overexpressed in the brain tissue and CNS cancers." (PMID 37049742, 2023). "For example, the MDM2 inhibitor RG7112, the first one to be admitted to clinical trials, although not yet extensively carried out, it provides a certain basis for molecular targeted treatment of gliomas." (PMID 36712862, 2022). "In one experiment, miRNA-129 inhibits glioma cell growth by targeting CDK4, CDK6, and MDM2." (PMID 36712862, 2022). "In glioma cells, AEG-1 interacted with MDM2, preventing ubiquitination and the subsequent proteasomal degradation, resulting in an increased stabilization of the MDM2 protein." (PMID 33918653, 2021). "KEGG pathway analysis also showed that the neighbor genes of WNT5A were widely distributed in multiple pathways in the de novo pathways of glioma occurrence, in which crucial oncogenes (EGFR and MDM2) and 2 important tumor suppressors (PTEN and IKN4a/ARF) were closely correlated with WNT5A." (PMID 32181818, 2020). "Finally, Go and KEGG analysis revealed WNT5A was associated with multiple signal translations, and crucial oncogenes (EGFR and MDM2) and 2 important tumor suppressors (PTEN and IKN4a/ARF) were found closely correlated with WNT5A in glioma." (PMID 32181818, 2020). "Furthermore, we discovered that CMIP upregulates MDM2, which is involved in the promoting role of CMIP in human glioma cells." (PMID 28744466, 2017). "The expression of MDM2 at ZT4 and ZT8 in glioma tissues were comparable (t=-0.098, p>0.5)." (PMID 29100427, 2017). "Here we have shown that MDM2 is positively regulated by CMIP and may participate in the promoting role of CMIP in human glioma cells." (PMID 28744466, 2017). "Our data show that a statistically robust 741-gene signature, correlated with MDM2 expression, exists in a large dataset of 122 PA tumors, but not other pediatric gliomas." (PMID 26378811, 2015).
glioma (continued). "Utilizing the R2 database tool, we analyzed genome-wide gene expression correlations with MDM2 (absolute correlation, FDR < 0.001) in PA and other gliomas to determine candidate programs that may lead to aneuploidy in these tumors." (PMID 26378811, 2015). "Aneuploid PA differentially expressed genes involved in CNS development, the unfolded protein response, and regulators of genomic stability and the cell cycle (MDM2, PLK2),whose correlated programs were overexpressed specifically in aneuploid PA compared to other glial tumors." (PMID 26378811, 2015). "This is in contrast with past evidence that there is no role for the levels of p21 or MDM2 proteins as a predictor of response to chemotherapeutics in glioma cell lines." (PMID 21366897, 2011). "Besides EGFR, which is found overexpressed in 40% of gliomas, the genes N-MYC, C-MYC, PDGFR-α, MYB, K-RAS, CDK-4 and MDM2 are the most commonly amplified oncogenes in gliomas." (PMID 18713462, 2008). "However, in these studies, the effects of MDM2 inhibitors were not examined using the differentiated or non-stem cell counterparts of glioma stem cell lines." (PMID 38612758, 2024). "Importantly, the knockdown of MDM2 induced more pronounced cell death in glioma stem cells than in their non-stem cell counterparts." (PMID 38612758, 2024). "The results obtained revealed that MDM2 was more highly expressed in stem cells (expressing the stem cell marker SOX2) than in non-stem cells (not expressing SOX2) in all three pairs of the glioma stem cell line and its non-stem cell counterpart examined." (PMID 38612758, 2024). "Notably, in contrast to a previous report in glioma cells, we saw a significant increase rather than decrease in MDM2 mRNA following YB-1 knockdown in both MSTO-211H and VMC23 cells, while REN cells showed no significant change." (PMID 32823952, 2020). "Therefore, MDM2 could be involved in the promoting role of CMIP in cell proliferation and metastasis of human glioma cells." (PMID 28744466, 2017). "In this study, we found that the mutant genes in the metastatic brain tumors included ALK, MDM2, ATM, BRCA1, FGFR1, and KRAS, and there were no glioma-related mutant genes (MGMT, IDH1, IDH2, 1p/19q, BRAF, and TERT)." (PMID 32973641, 2020).